CRP (C-reactive protein)
Diseases named in the same sentence as CRP in open-access papers (continued):
Sharing a sentence is not in itself a finding about the gene and the disease.
Sepsis (continued). "The usefulness of sepsis biomarkers, such as procalcitonin (PCT) and presepsin (PSEP), has been reported; PCT and PSEP have been reported to be superior to C-reactive protein (CRP) and interleukin-6 for sepsis diagnosis and assessment of sepsis severity." (PMID 28702197, 2017). "Higher level of serum Creatinine, BUN, CRP and PCT were found among the patients with sepsis who developed AKI." (PMID 28296904, 2017). "The CRP level and PCT level in the sepsis/SS group was significantly higher than that of the non-sepsis group." (PMID 28764651, 2017). "The ROC analysis showed that the AUCs of hs-CRP and PCT for the discrimination of septic shock patients from sepsis patients were 0.751 (95% CI: 0.62-0.88; P = 0.002) and 0.719 (95% CI:0.57-0.86; p = 0.007), respectively." (PMID 28764651, 2017). "C. Preininger group presented an RNA aptamer and antibody-based biosensor for the detection of C-reactive protein (CRP), which has been identified as a biomarker for inflammation, sepsis and tissue necrosis." (PMID 28293287, 2017). "Studies have shown that, compared with the known biomarkers currently in use, such as C-reactive protein (CRP), PCT has a higher sensitivity and specificity for severe sepsis and septic shock diagnosis." (PMID 29312224, 2017). "Procalcitonin (PCT) and C-reactive protein (CRP) are the most frequently used biomarkers in the diagnosis and management of sepsis." (PMID 29104224, 2017). "These include the three most used biomarkers for sepsis in clinical practice: procalcitonin (PCT), C-reactive protein (CRP) and lactate." (PMID 29104224, 2017). "This study showed that ROCAUC of sCD14-ST, CRP, and TBIL on sepsis are significantly different (P < 0.05)." (PMID 28758124, 2017). "To determine the predictive value of GDF-15 in identifying sepsis at admission, we conducted a ROC analysis comparing GDF-15 with classical markers such as procalcitonin and C-reactive protein (CRP)." (PMID 29180833, 2017). "A ROC analysis showed that the area under the curves (AUC) of hs-CRP and PCT for the discrimination of sepsis/SS patients were 0.825 (95% confidence interval[CI]: 0.73-0.92; P < 0.001) and 0.819 (95%CI:0.72-0.92; p < 0.001), respectively." (PMID 28764651, 2017). "The CRP level and PCT level in the septic shock group was significantly higher than that in the sepsis group." (PMID 28764651, 2017). "A previous study demonstrated that, compared with white blood cells (WBCs) or CRP levels, DNI is a more useful marker for predicting mortality in patients with sepsis." (PMID 28320333, 2017). "Their value added on top of Sequential (Sepsis-related) Organ Failure Assessment (SOFA) score, high-sensitivity C-reactive protein, and white blood cells was also analyzed." (PMID 28271449, 2017). "As measurements of markers like CRP and PCT can be obtained much earlier than culture results, they are very useful in the early diagnosis of sepsis." (PMID 27348760, 2017). "In this study, we found that CRP was well correlated to the SOFA score, which made hs-CRP an adequate biomarker to reflect the severity of sepsis in oldest old patients." (PMID 28764651, 2017). "There were significant differences in the patients’ characteristics of APACHE II score, SOFA score, CRP level, PCT level, and RIPK3 level at 24 hours after sepsis diagnosed among three groups." (PMID 29137405, 2017). "C-reactive protein (CRP) and procalcitonin (PCT) are among the current most promising biomarkers of sepsis." (PMID 28235076, 2017). "Currently, serum C-reactive protein (CRP) and procalcitonin (PCT) have been evaluated routinely for sepsis diagnosis." (PMID 27991579, 2016). "Thus, although CRP has been one of the best-known inflammatory biomarkers formany decades, the dynamic and judicious use of CRP combined with clinicalcriteria and/or other biomarkers has great value and should be consideredsystematically in sepsis treatment evaluation." (PMID 28099644, 2016).
Sepsis (continued). "Because results of initial liver function tests, including clotting, were normal, and C-reactive protein (CRP) response was adequate, the impression was of bacterial (or fungal) septicemia and renal failure." (PMID 27648582, 2016). "CRP and PCT was increased (p < 0.001) and TCH, HDL-C and apoA1 (p < 0.001) were decreased in the sepsis patients." (PMID 27462492, 2016). "This is in line with previous studies investigating patients with sepsis or septic shock that found PCT and CRP to have limited abilities to predict outcome." (PMID 26880104, 2016). "In the newly hospitalized patient subgroup (n = 86), univariate analysis revealed that CRP, PCT and SOFA were statistically significant in diagnosing sepsis." (PMID 27287669, 2016). "In the sepsis group; age, APACHE II and SOFA scores, length of ICU stay, mortality, CRP and NLCR were significantly higher than non-sepsis SIRS group (p<0.001 for each)." (PMID 26863002, 2016). "Numberous diagnostic biomarkers have been investigated in pediatric and adult sepsis, including procalcitonin (PCT) and C-reactive protein (CRP),either to identify bacterial infection or differentiate septic patients from those with SIRS." (PMID 27089280, 2016). "Similar results of preference of procalcitonin over CRP was reported in discriminating SIRS and sepsis and also as a marker for detection of early VAP or VAP in patients with a successful cardiopulmonary resuscitation." (PMID 28469676, 2016). "For example, the level of blood C-reactive protein (CRP), cytokines, procalcitonin (PCT) and lipopolysaccharide (LPS)-binding protein are elevated in sepsis." (PMID 27788141, 2016). "Univariate analysis of the measured raw patient parameters using a ROC curve showed that CRP, PCT and SOFA were significant for the diagnosis of sepsis." (PMID 27287669, 2016). "Therefore, CRP could be influenced by numerous confounding factors during sepsis and we could not demonstrate the positive association between CRP level and NeOAF in our study." (PMID 27855722, 2016). "In a subgroup of patients that underwent surgical procedures (n = 160), univariate analysis determined significance for only CRP and PCT in sepsis diagnosis." (PMID 27287669, 2016). "Some studies have reported that in cases of sepsis or CAP, sTREM-1 is a superior indicator of bacterial disease compared with CRP and PCT." (PMID 27846213, 2016). "Cut off values of CRP, LymC, NeuC, NLCR and PLTC for sepsis were ≥4.0, <0.45, ≥10.0, ≥14.2 and <150." (PMID 26863002, 2016). "While WBCC, NeuC, EoC and Neu% do not have any contribution towards distinguishing sepsis from non-sepsis SIRS, combinations of CRP, LymC and PLTC can be used to determining sepsis at the ICU admission." (PMID 26863002, 2016). "CRP, a marker for SIRS and sepsis, were increased in nearly all cases of the present study, indicating systemic inflammation." (PMID 27978832, 2016). "To date, C-reactive protein (CRP) and procalcitonin (PCT) are the most widely used markers for sepsis management in neonatal intensive care unit (NICU)." (PMID 26720209, 2015). "Of the patients with definite sepsis, 55% had an abnormal WBC count, 23% had thrombocytopenia (that is, platelet count <150 × 109/L) and 97% had a raised CRP level (>5 μg/ml)." (PMID 25887201, 2015). "Various biological markers such as PCT, CRP, interleukins, and myeloid cells expressing triggering receptor-1 (TREM-1) have been reported as biomarkers in diagnosis with sepsis." (PMID 26642970, 2015). "At present, various biomarkers (alone or in combination) are used in the diagnosis of sepsis, including procalcitonin (PCT), C-reactive protein (CRP), interleukin (IL), and soluble form of triggering receptor expressed on myeloid cells-1 (Strem-1)." (PMID 26192602, 2015). "The positive likelihood ratios of blood culture and CRP reflect the poor performance of these tests in the VLBW and confirm the superiority of 16S RT-PCR to diagnose sepsis in these infants." (PMID 26305781, 2015).
Sepsis (continued). "Some studies have shown that it is possible to predict the outcome of sepsis based on changes in PCT and CRP." (PMID 26367532, 2015). "In 15 patients fulfilling the criteria for severe sepsis, we measured plasma-NGAL, plasma Crea and eGFR, CRP, leukocyte count as well as IL-6, IL-8 and IL-10." (PMID 25893429, 2015). "Leukocytosis, elevated C-reactive protein (CRP), and increased procalcitonin are known as traditional markers for sepsis." (PMID 26692209, 2015). "Some of them are already in use in clinical settings: C-reactive protein (CRP) and procalcitonin (PCT), synthesized in the acute phase of sepsis, are routinely used as complementary tools in clinical decision-making." (PMID 26557154, 2015). "ROC curve analysis revealed a rather low prognostic power of OPN for predicting long-term mortality, which was still superior to that of CRP and PCT as established markers of SIRS/sepsis or other markers of organ failure." (PMID 26111529, 2015). "The most used biomarkers for sepsis are procalcitonin (PCT), C-reactive protein (CRP), and interleukin 6 (IL-6)." (PMID 26221578, 2015). "Compared to traditional biomarkers of inflammation (such as WBC and CRP), PSP emerged not only as a promising biomarker for sepsis but also as a predictor for clinical outcomes including sepsis or death at the ICU." (PMID 25793700, 2015). "The phylum Firmicutes and the families Streptococcaceae and Lactobacillaceae were negatively correlated with many inflammatory markers of sepsis progression, such as IL-6, IL-18, HMGB1 and CRP." (PMID 25881250, 2015). "In VLBW infants this universal molecular assay performed better in the diagnosis of late onset sepsis (LOS) than blood culture and CRP." (PMID 26305781, 2015). "Currently the measurement of plasma C-reactive protein (CRP) and procalcitonin (PCT) has been utilized in diagnosing and monitoring neonatal sepsis, severe sepsis and septic shock, at the onset and in the course of the disease." (PMID 26063982, 2015). "(iii) Compared with CRP, PCT is a relatively specifical marker of infection such as respiratory infection or sepsis." (PMID 25694861, 2015). "A correlation between presepsin and inflammatory biomarkers, such as CRP, WBC, IL-6 and PCT, can be explained by the ongoing systemic activation of inflammatory biomarkers during severe sepsis and septic shock." (PMID 25190134, 2014). "But the study of patients with SIRS showed that PTX3 and CRP had similar performance in discriminating between SIRS and sepsis." (PMID 25530683, 2014). "Blood biochemical parameters, such as C-reactive protein (CRP) and procalcitonin (PCT) have been considered to evaluate the evolution of infections and sepsis in critically ill patients." (PMID 25926862, 2014). "In contrast with CRP results, PCT levels increased in patients with more severe organ dysfunction, severe sepsis, or septic shock." (PMID 25407928, 2014). "CRP (C-reactiveprotein) and PCT (procalcitonin) are the most commonlyused protein biomarkers for patients with sepsis." (PMID 24303815, 2014). "Decreased fibrinolytic activity, as reflected by the lysis index, was found to discriminate sepsis from postoperative SIRS patients (ROC-AUC, 0.811; sensitivity, 93%; specificity, 50%), which was comparable to CRP and procalcitonin." (PMID 24512650, 2014). "Procalcitonin (PCT) and C-reactive protein (CRP) have been most widely used, but even these have limited abilities to distinguish sepsis from other inflammatory conditions or to predict outcome." (PMID 24800240, 2014). "Biochemical tests were consistent with sepsis and chronic inflammation, with raised total white count, polyclonal gammopathy and elevated erythrocyte sedimentation rate (ESR), and C-reactive protein (CRP) levels." (PMID 25221681, 2014). "The most commonly used biomarkers of sepsis in routine clinical diagnostics are procalcitonin (PCT) and C-reactive protein(CRP)." (PMID 24809055, 2014).
Sepsis (continued). "Neutropenia was complicated by sepsis with elevated procalcitonin (PCT: 13.6 ng/ml) and C-reactive protein (CRP: 259 mg/l) one week after the 4th bolus of cyclophosphamide." (PMID 24495297, 2014). "In the present study the utility of serial qualitative C-reactive protein (CRP) assay and white blood cells count (WBC) in the diagnosis of neonatal septicaemia was investigated using blood culture as gold standard." (PMID 25280754, 2014). "The IL-2 induced toxicity shares many features with sepsis such as capillary leakage, systemic complement activation, and a relatively non-specific rise in inflammatory mediators such as TNF-alpha, C-reactive protein, and in advanced cases organ failure." (PMID 24884532, 2014). "Combination of first CRP and RNOS had sensitivity of 95.6% while overall specificity decreased to 56.4%, while serial CRP and neonatal scale of sepsis had sensitivity of 89.1% and specificity was found to be 74.0%." (PMID 25475836, 2014). "The mean values of the CRP and PCT concentrations and the WBC count in the sepsis group were 9.99 mg/dl, 17.86 ng/ml and 15,620 cells/ml, respectively, versus 3.31 mg/dl, 0.34 ng/ml and 8,360 cells/ml, respectively in the non-sepsis group (P<0.001)." (PMID 24669245, 2014). "We found a single CRP and RNSOS to have a very good sensitivity (96.0%) in identifying neonates with sepsis but had relatively low specificity (56.4%) in excluding non-cases." (PMID 25475836, 2014). "These molecules include C-reactive protein (CRP), procalcitonin (PCT), several cytokines, and cell surface markers, though only 20% have been assessed for use in the diagnosis of sepsis." (PMID 25430913, 2014). "Based on these findings CRP and WBC counts can be used as inexpensive methods to diagnose neonatal septicaemia in developing countries in order reduce the duration of antibiotics treatment hence preventing resistance development." (PMID 25280754, 2014). "We also compared the performance of the IG count with CRP, LBP and IL-6, which are parameters commonly evaluated in patients with suspected infection or sepsis." (PMID 23398965, 2013). "As has been repeatedly noted by authors critical of PCT as a sole indicator of sepsis, PCT should be viewed together with other information, including fever, leukocyte count and very importantly, CRP." (PMID 23590389, 2013). "Markers such as interleukin-6 (IL-6), C-reactive protein (CRP) and lipopolysaccharide binding protein (LBP) have been proposed for diagnosing or monitoring sepsis." (PMID 23398965, 2013). "Plasma levels of C-reactive protein (CRP) or procalcitonin (PCT) are often used to increase the a priori probability of microbial infection and sepsis in the intensive care unit (ICU)." (PMID 23762396, 2013). "The optimal cut-off value for PTX3 in predicting severe sepsis was 14.1 ng/ml (specificity 80% and sensitivity 63%), for PCT 0.30 ng/ml (specificity 66% and sensitivity 82%) and for CRP 158 mg/l (specificity 70% and sensitivity 47%)." (PMID 23341967, 2013). "In this randomized controlled study, we did not observe significant differences between the two groups in CRP levels (a standard infection marker), PCT levels (which are thought to reflect the severity of sepsis), ICU stay duration, and patient prognoses." (PMID 25705399, 2013). "We found the same phenomenon that, on the admission day, the sepsis group exhibited a higher level of sTREM-1, sCD163, PCT, and CRP than the SIRS group." (PMID 23935252, 2013). "CRP and PCT changes have been compared in their relative ability to detect the evolution of infection or sepsis, within or outside the ICU." (PMID 23762396, 2013). "The SAA test showed moderate accuracy in the diagnosis of NS both at the first suspicion of sepsis and 8–96 h after the sepsis onset, both with Q* = 0.91, which is similar to the PCT and CRP tests for the diagnosis of NS in the same period." (PMID 23984377, 2013).
Sepsis (continued). "On the first day of ICU enrollment, the sepsis group exhibited a higher level in serum sTREM-1, serum sCD163, PCT, and CRP than the SIRS group." (PMID 23935252, 2013). "In the sepsis group, the AUCs for the levels of FT3, NT-proBNP and CRP and the APACHE II score to predict ICU mortality were 0.633 ± 0.055, 0.666 ± 0.054, 0.627 ± 0.056 and 0.755 ± 0.045, respectively (all P < 0.05)." (PMID 22257427, 2012). "Biochemical markers that are believed to help in early diagnosis of sepsis include procalcitonin (PCT), interleukin 1 (IL 1), IL 6, IL 10 and C-reactive protein (CRP), although reports of sensitivity and specificity differ." (PMID 22742451, 2012). "On ICU day 1, the sepsis group had higher serum sTREM-1, PCT, and CRP levels compared with the SIRS group (P <0.05)." (PMID 22809118, 2012). "In our study, on day 1 of their admission to an ICU, the serum sCD163 levels in sepsis patients were markedly higher than in SIRS patient, and were superior to common infection-related variables (CRP and PCT) for diagnosing sepsis." (PMID 22911680, 2012). "The chip for biomarker detection of sepsis comprises multi-analyte on-chip immunoassays which include both sandwich (cytokines, PCT, S-100, E-Selectin) and binding inhibition formats (CRP, neopterin)." (PMID 22438722, 2012). "In the sepsis subgroup, the AUC for FT3, NT-proBNP and CRP levels (0.633 ± 0.055, 0.666 ± 0.054 and 0.627 ± 0.056, respectively) were close but much smaller than the APACHE II score (0.755 ± 0.045)." (PMID 22257427, 2012). "Our study, on the other hand, found that on the day of ICU admission, the sepsis group had higher sTREM-1, PCT, and CRP levels and APACHE II scores than did the SIRS group." (PMID 22809118, 2012). "Biomarkers, such as C-reactive protein [CRP] and procalcitonin [PCT], are insufficiently sensitive or specific to stratify patients with sepsis." (PMID 22748193, 2012). "ROC curves were obtained for sTREM-1, PCT, and CRP levels and APACHE II scores, which were significantly different between the SIRS and sepsis groups." (PMID 22809118, 2012). "There are a limited number of studies that describe baseline C-reactive protein (CRP) (an inflammatory marker) level, and its changes in response to therapy, as a predictor of sepsis mortality." (PMID 23171626, 2012). "To compare the usefulness of CRP, PCT, IL-6, and LBP in differentiating sepsis from SIRS we used the highest level of each in the first 24 hours of admission." (PMID 21687569, 2011). "At admission to the ICU, serum NT-proCNP concentrations in the total cohort and the subgroup of sepsis patients were closely correlated to markers of inflammation and bacterial infection, such as PCT, CRP and TNF-α." (PMID 21281508, 2011). "During the first 14 days of postoperative sepsis, LBP plasma concentrations showed a time course that was very similar to CRP with a high concordance in the pattern of day-to-day changes." (PMID 21901123, 2011). "However, some limitations also merit consideration: The prognostic accuracy of LBP and CRP may have been negatively influenced in our study population, because LBP and CRP are frequently unspecifically elevated after major surgery to levels comparable to those seen in sepsis." (PMID 21901123, 2011). "On admission CRP, PCT, IL-6, and LBP levels were all significantly higher in patients with sepsis in comparison to patients with SIRS." (PMID 21687569, 2011). "Compared with the tendency for changing levels of CRP and PCT, the gradual increase of sTREM-1 levels was a better reflection of the progression of sepsis, which was of greater value for predicting death." (PMID 21356122, 2011). "CRP, PCT, IL-6 and LBP levels were significantly higher in patients with sepsis as compared to SIRS." (PMID 21687569, 2011). "CRP and PCT have been extensively studied and compared for their efficacy to diagnose sepsis cases in young infants." (PMID 23198119, 2011).